CD276 (CD276 molecule)
Description:
May participate in the regulation of T-cell-mediated immune response. May play a protective role in tumor cells by inhibiting natural-killer mediated cell lysis as well as a role of marker for detection of neuroblastoma cells. May be involved in the development of acute and chronic transplant rejection and in the regulation of lymphocytic activity at mucosal surfaces. Could also play a key role in providing the placenta and fetus with a suitable immunological environment throughout pregnancy. Both isoform 1 and isoform 2 appear to be redundant in their ability to modulate CD4 T-cell responses. Isoform 2 is shown to enhance the induction of cytotoxic T-cells and selectively stimulates interferon gamma production in the presence of T-cell receptor signaling.
Synonyms: B7-H3; B7H3; B7RP-2; 4Ig-B7-H3
Tractability: Antibody: a drug acting on it is in phase 2 or 3 trials; UniProt predicts a signal peptide or a membrane-spanning region. PROTAC: ubiquitination databases record sites on it; its protein half-life has been measured.
Target class: Surface antigen
Gene: Protein-coding gene on chromosome 15 (73,683,966 to 73,714,518, forward strand). Ensembl gene ENSG00000103855.
Subcellular location: Membrane
Subcellular location (Human Protein Atlas): Vesicles
Gene Ontology:
Molecular function: protein binding; signaling receptor binding
Biological process: positive regulation of T cell proliferation; positive regulation of type II interferon production; T cell activation; regulation of cytokine production; regulation of immune response; T cell receptor signaling pathway; positive regulation of cytokine production; regulation of type II interferon production
Cellular component: external side of plasma membrane; membrane
Genetic constraint (gnomAD): Loss-of-function variants: 34 observed, 51 expected, observed/expected ratio (o/e) 0.67, 90% interval 0.51 to 0.89. The upper end of that interval is the gene's LOEUF score, 0.89, which puts it in group 3 of 6, group 1 being the genes least tolerant of losing a copy. Missense variants: 634 observed, 732.03 expected, observed/expected ratio (o/e) 0.87, 90% interval 0.81 to 0.93. Synonymous variants: 275 observed, 316.72 expected, observed/expected ratio (o/e) 0.87, 90% interval 0.79 to 0.96.
Homologues: Orthologues: chimpanzee CD276 (99% identical), dog CD276 (93% identical), macaque CD276 (55% identical), rat Cd276 (53% identical), mouse Cd276 (53% identical), zebrafish cd276 (29% identical), tropical clawed frog cd276 (28% identical). Paralogues in human: BTN1A1 (17% identical), BTNL9 (15% identical), ICOSLG (15% identical), BTNL8 (14% identical), BTN3A3 (14% identical), BTN3A1 (14% identical), BTN2A2 (13% identical), BTNL3 (13% identical), BTN2A1 (13% identical), HHLA2 (12% identical), BTN3A2 (11% identical), BTNL2 (11% identical), and 3 more.
Diseases named in the same sentence as CD276 in open-access papers:
CD276 is named in the same sentence as 303 diseases in open-access papers, as found by Europe PMC text mining. Sharing a sentence is not in itself a finding about the gene and the disease. The quoted sentences say what the papers report.
glioma (160 papers, 2014 to 2026). A benign or malignant brain and spinal cord tumor that arises from glial cells (astrocytes, oligodendrocytes, ependymal cells). "CD276 is strongly expressed in most types of cancer and is associated with the poor prognosis of glioma." (PMID 37510310, 2023). "Isocitrate dehydrogenase (IDH) mutation also seems to influence differential expression of CD276 between the grade II and higher-grade gliomas." (PMID 31075138, 2019). "In the meantime, CD276 could be down-regulated in IDH mutated gliomas, mainly caused by autophagy induced by 2-HG accumulation." (PMID 34565408, 2021). "CD276 also seems to favor its expression in H3 mutated gliomas, which is exclusive to IDH mutation." (PMID 34565408, 2021). "The immune checkpoint protein B7-H3 (CD276) is significantly overexpressed in glioma and multiple other solid tumors, highlighting its potential as a diagnostic biomarker and therapeutic target." (PMID 41660513, 2026). "At the protein level, both SMARCAL1 and CD276 were also more highly expressed in glioma cell lines than in NHA." (PMID 39994264, 2025). "CD276 also induced glioma cell proliferation and invasion via upregulation of the JAK2/STAT3/Slug pathway." (PMID 40801642, 2025). "We first analyzed the expression levels of SMARCAL1 and CD276 in glioma cell lines (U118-MG, U87-MG, A172) and the normal human astrocyte (NHA) cell line." (PMID 39994264, 2025). "In this study, we demonstrated a strong correlation between aurora kinase A (AURKA) and CD276 expression in glioma tissue samples." (PMID 39928563, 2025). "Our PathoFusion heatmaps show examples of diffuse glioma growth where strongly Iba1+ immunoreactive microglia-derived macrophages are found in spatial proximity to CD276+ GSCs, outnumbering instances where CD163 and CD276+ cells co-occur." (PMID 40136662, 2025). "We confirmed the role of CD276 in promoting tumor progression and reducing survival outcomes in glioma through immunohistochemical analysis." (PMID 38365809, 2024). "According to the Ivy Glioblastoma Atlas Project, MAP2K3, CD68 and CD276 were found to be upregulated in human glioma samples in the Perinecrotic zone (CTpnz) region of expression." (PMID 38938778, 2024). "The B7 homolog 3 (CD276 or B7-H3), a member of the B7 immune checkpoint family is rather specifically expressed in many human cancers, including glioma, ovarian cancer, neuroblastoma, lung adenocarcinoma, pancreatic cancer, certain sarcomas, and AML." (PMID 38637557, 2024). "We have analysed cellular labelling for CD276, a protein of great interest in cancer immunology and a potential marker of malignant glioma cells/putative glioma stem cells (GSCs)." (PMID 38398141, 2024). "We employed 144 cases of glioma patients from 2008 to 2010 and the expression of CD276 was assessed using immunohistochemistry (IHC)." (PMID 38365809, 2024). "The example used in this study is CD276 expression by malignant glioma cells/putative glioma stem cells (GSCs)." (PMID 38398141, 2024). "Our CD276 dataset consists of high-grade glioma cases from the Australian Genomics and Clinical Outcomes of Glioma (AGOG) repository." (PMID 38398141, 2024). "CD276, an important immune checkpoint molecule, was confirmed to be a marker of malignant glioma cells/putative glioma stem cells (GSCs)." (PMID 38398141, 2024). "CD276 (B7-H3), a member of the B7 family of cell surface receptors, has been found to be an adverse prognostic factor for the patients with glioma." (PMID 38066643, 2023). "Other checkpoint proteins of importance in glioma biology include the immunomodulator B7-H3 (CD276) and the tryptophan-degrading enzyme indoleamine-2,3-dioxygenase (IDO1)." (PMID 38275375, 2023). "Guo and colleagues reported considerable expression of CD276 in high-grade gliomas, which has led to trials of antibody- and CAR-T cell-based immunotherapeutic approaches." (PMID 38275375, 2023).
glioma (continued). "CD276 belongs to the immunomodulatory B7 family and is overexpressed in a variety of tumors, including gliomas." (PMID 38275375, 2023). "These immune check points Programmed death-ligand 1 (PDL-1), B7-H3 (CD276), and B7-H6 (NCR3LG1) have been associated with aggressiveness and poor prognosis in glioma patients." (PMID 37261362, 2023). "Better elucidating the involvement of CD276 pathway in immune responses will promote the great development of immunotherapy for glioma." (PMID 35928223, 2022). "In gliomas of SGMRS high-risk group, the expression levels of CD274 (PD-L1), CD276 (B7-H3), and CD279 (PD-1) were remarkably higher compared to the low-risk group in TCGA cohort." (PMID 36467068, 2022). "CD276, as the most strongly associated ICG, was selected among 313 glioma samples from the CGGA database to verify the relationship with the hub genes." (PMID 35896732, 2022). "Gliomas of TrMRS high-risk group presented with significantly higher expression level of CD274 (PD-L1), CD276 (B7H3), HAVCR2 (TIM3), PD1 (CD279, PDCD1), and CD44." (PMID 36386216, 2022). "Immunohistochemistry was used to assess PTX3 expression, HAVCR2, PD‐1, PD‐L1, and CD276 in glioma sections from the Xiangya cohort (n = 60)." (PMID 35855654, 2022). "In CGGA dataset, PDIA5 expression was positively associated with CD276, CD274, PDCD1LG2, and HAVCR2 in pan-glioma and LGG patients, and positively correlated with CD276, PDCD1, CD274, PDCD1LG2, and HAVCR2 in GBM patients." (PMID 33664747, 2021). "In TCGA datasets, there was positive correlation between PDIA5 and CD276 or PDCD1LG2 in pan-glioma patients, and PDIA5 expression was positively associated with CD276, PDCD1LG2 and HAVCR2 in LGG patients." (PMID 33664747, 2021). "The higher expression of CD276 showed poor prognosis in glioma patients from CGGA and TCGA; this was also consistent with the present data." (PMID 31075138, 2019). "Potent monoclonal antibody of CD276 is already available and has been reported as being safe for treatment of advanced-stage central nervous system cancer in children." (PMID 27329595, 2016). "Immunotherapy targeting B7-H3 (CD276) has shown promising efficacy in the treatment of gliomas." (PMID 39928563, 2025). "B7-H3: The checkpoint molecule B7 H3 (CD276) is strongly expressed in gliomas, including DIPG." (PMID 40940995, 2025). "Notably, the most relevant immune checkpoint gene is CD276 in Glioma (R = 0.49), LUAD (R = 0.74), LIHC (R = 0.60), KIRC (R = 0.63), and UCEC (R = 0.68)." (PMID 39994264, 2025). "A recent study discovered that the immune-checkpoint proteins CD276, programmed cell death ligand (PD-L) 1, and PD-L2 were expressed by the TAMs that engulfed the glioma cells and that this led the TAMs to become M2-like that drove immunosuppression by inhibiting the growth of activated T cells." (PMID 39691192, 2024). "We found that B7-H3 (encoded by the gene CD276) is highly expressed in all stages of glioma compared to normal brain tissue." (PMID 38561797, 2024). "In addition, CD276 not only predicts the poor prognosis in glioma, but also serves as an effective target for chimeric antigen receptor T cells targeting glioma." (PMID 38173030, 2024). "A unique understanding of the combination of anti-CD276 and anti-angiogenesis revealed by using antibody–drug conjugates to ablate CD276+glioma cells concurrently impairing tumour vascular, which was reinforced by the confirmation that CD276 was positively correlated with VEGFA and MMP2." (PMID 38523646, 2024). "The phenotypes of 4Ig and 2Ig in glioma are unclear, and the regulatory molecular mechanism is still unknown, which is unfavourable to the CAR‐T target design of CD276 for glioma immunotherapy." (PMID 39048916, 2024). "In gliomas, B7-H3 (CD276), an immune checkpoint, modulates the TME and T-cell function." (PMID 38342925, 2024). "Similarly, the over-expression of B7-H3 (CD276) in central nervous system tumors has led to trials of intraventricular B7-H3 CAR-T cells (NCT04185038)." (PMID 39766049, 2024).
glioma (continued). "Correspondingly, Siglec15 could potentially interact with immune-related checkpoints, including PD1, PDL1, PDL2 and CD276 (B7-H3), implying a pivotal immunoregulatory role of Siglec15 in the glioma immune microenvironment." (PMID 37325664, 2023). "Immunotherapy targeting CD276 may be effective in patients with glioma with high expression of CENPA." (PMID 36341103, 2022). "Using antibody–drug conjugates to ablate CD276 + glioma cells simultaneously impaired tumor vescular, indicating a novel insight on the combination of anti-CD276 with anti-angiogenesis, which was supported when CD276 was confirmed to positively be related with VEGFA and MMP2." (PMID 35135556, 2022). "CD276 has been documented to mediate glioma immune escape and increase glioma aggressiveness." (PMID 36341103, 2022). "CD276 is a putative target for CAR T-cell therapy of pediatric glioma." (PMID 34722280, 2021). "ANXA1 and CD276 (Patient id: 3,174; 3,241) also were overexpressed in high grade gliomas." (PMID 34422796, 2021). "CD276 is present at low levels in normal tissues but is overexpressed by bladder, breast, cervical, colorectal, esophageal, glioma, kidney, liver, lung, ovarian, pancreatic, prostate, liver, oral squamous cell carcinoma, endometrial cancer, squamous cell carcinoma, and gastric cancer cells." (PMID 34680929, 2021). "Interestingly, TCGA, CGGA and Rembrandt data analysis showed that CD276 gene expression negatively predicted survival of patients with GBM or glioma." (PMID 33795013, 2021). "CD276 antigen has been reported to be upregulated in high-grade glioma." (PMID 32922940, 2020). "In this study, by analyzing the Chinese Glioma Genome Atlas (CGGA) and the Cancer Genome Atlas (TCGA) databases, we found that aurora kinase A (AURKA) expression is positively correlated with CD276 expression." (PMID 39928563, 2025). "Correlation analysis revealed that the expression levels of CD48, CD276, and CD274 proteins in glioma were significantly correlated with their mRNA levels (r > 0.6, p < 0.05)." (PMID 40606983, 2025). "The results of our investigation showed a strong relationship between the expression of SMARCAL1 and several immune checkpoint genes, including CD276, NRP1, TNFSF4, CD40, CD200, and CD80 in Glioma, LUAD, LIHC, KIRC, and UCEC." (PMID 39994264, 2025). "In recent years, in the development of emerging immunotherapy, B7‐H3 is also termed as CD276 and has become a novel chimeric antigen receptor (CAR)‐T target against glioma and other tumours, and aroused extensive attention." (PMID 39048916, 2024). "At different E:T ratios, CD276 CAR-T showed high killing efficiency (cytolysis > 80%) against different human cancer cell lines, including liver cancer, glioma, renal cancer, fibrosarcoma, breast cancer, ovarian cancer and colon cancer." (PMID 38978106, 2024). "Then, we selected the top 5 relevant immunomodulators, including an immunostimulator (CD276), two immunoinhibitors (IL10RB and TGFBR1), a chemokine (CXCL10) and an MHC (HLA-A), in the glioma dataset and drew scatterplots to show their details." (PMID 37006287, 2023). "We found that cluster 2 had a remarkably high expression level of most of the immune checkpoints including PD-1 (PDCD1), PD-L1 (CD274), and CTLA-4 (CD276), and most of these trends were consistent between IDH-mutant and IDH-wildtype gliomas." (PMID 36970537, 2023). "In our study, Siglec15 was broadly and positively correlated with immune checkpoints that have been reported as potential biomarkers of glioma, such as PD1, PDL1, PDL2, Lag3, CTLA4, TIGIT, CD276 (B7-H3), IDO1 and CD47." (PMID 37325664, 2023). "•B7–H3 (CD276) is a transmembrane protein highly expressed in brain tumors such as ATRT, DIPG, DMG, medulloblastomas, and high-grade gliomas." (PMID 38023730, 2023). "CAR T cells have been developed to target the antigens B7-H3 (CD276), GD2, EGFR, IL13Ra2 and HER2 in a range of brain cancers such as medulloblastoma, glioma and ependymoma." (PMID 35456250, 2022).
glioma (continued). "Based on the TCGA and CGGA datasets, we proved that PTX3 positively correlated with CD276, CD274, PDCDL1LG2, HAVCR2, CD80, IDO1, and PDCD1 in pan‐glioma, GBM, and LGG." (PMID 35855654, 2022). "In our research, PTX3 is highly correlated with PD‐1, PD‐L1, CD274, CD276, and HAVCR2, all of which can mediate immune escape of gliomas." (PMID 35855654, 2022). "We investigated the immune checkpoint expression in glioma specimens and uncovered that CD274 (PD-L1), PDCD1, PDCD1LG2, CTLA4, CD276, HAVCR2, and LAG3 were significantly overexpressed in the high DDR score subtype." (PMID 35720326, 2022). "Other immune checkpoints that are targeted by drugs for clinical use, including B7H3 (CD276) and TIM3 (HAVCR2), were also found to be highly expressed in patients with high-HIF1A-expression gliomas." (PMID 34305618, 2021). "TOX was strongly correlated with CD276, IDO1, PDCD1LG2 (PD-L2), and VTCN1 in pan-glioma analysis and GBM alone in both TCGA and CGGA cohorts." (PMID 32762688, 2020). "TOX had high correlation with CD276, IDO1, PDCD1LG2, and VTCN1 in both pan-glioma analysis and GBM alone." (PMID 32762688, 2020). "It has been shown that the B7 family members, especially B7-H1 (PD-L1), B7-H3 (CD276), and B7-H4 (VTCN1), are involved in immune escape in several types of tumors including glioma." (PMID 32322592, 2020). "124I-Omburtamab is a monoclonal antibody that targets the membrane-bound protein CD276 (B7-H3), an immune modulator part of the B7 superfamily overexpressed in DIPG and other pediatric CNS cancers." (PMID 32674336, 2020). "CD276 (B7-H3) is an immune checkpoint molecule that belongs to the CD28 family, which plays pivotal roles in T-cell suppression in glioma." (PMID 31075138, 2019). "Similar to IL-33 and its downstream mediator IL-6, CD276 may have a role in the activation of STAT3 downstream signaling, which enhances stem-like characteristics in glioma cells and induces an anti-inflammatory phenotype in TAMs." (PMID 40136662, 2025). "However, MAPKAPK2 is positively correlated with a series of immune regulators such as CD274, CD276, PDCD1, and CD70, which probably affect the tumor killing effect of the infiltrated immune cells in glioma tissue." (PMID 38322416, 2024). "Immunohistochemical staining of CD276 in 144 cases further validated its negative correlation with OS in glioma." (PMID 38365809, 2024). "Focusing on Gliomas: NCT01502917, a phase 1 clinical trial tested the safety and efficacy of 124I-omburtamab, a monoclonal antibody labeled with 124I targeting CD276 delivered by convection-enhanced delivery (CED) in patients with diffuse intrinsic pontine glioma (DIPG)." (PMID 38539537, 2024). "Nevertheless, the possibility of encountering clinically negative CD276 glioma patients is worthy of our serious thinking about new solutions beyond CAR‐T against CD276." (PMID 39048916, 2024). "B7-homolog 3 (B7-H3) alias CD276, a member of the B7 family of immune checkpoint inhibitors, is expressed in cases of hematological cancers and solid tumors including higher grades of glioma." (PMID 36721153, 2023). "Through analysis of glioma samples in the CGGA and TCGA databases, we found that CDCA7 expression level was significantly correlated with tumor-related immunosuppressive molecules, including CD80, CD276, CD28, PDCD1LG2, and TNFSF4." (PMID 37510310, 2023). "Correspondingly, it showed that CD101 expression could potentially interact with numerous immune-relevant genes, including CD276, CD274, CD80, CTLA4, and PDCD1, implying an immunoregulatory role of CD101 in the glioma immune microenvironment." (PMID 35350788, 2022). "In agreement, REMBRANDT, TCGA and CGGA database analysis revealed a higher level of mRNA coding for B7-H3 (CD276) in GBM compared to non-cancerous brain tissues or lower grades gliomas; oligodendroglioma, oligoastrocytoma and astrocytoma." (PMID 33795013, 2021).
glioma (continued). "B7-H3 (CD276) overexpression has been found in a variety of human cancers, including lung adenocarcinoma, craniopharyngioma, neuroblastoma, medulloblastoma, glioma, ovarian cancer, pancreatic cancer, and acute myeloid leukemia." (PMID 32903405, 2020). "Interestingly, seven urinary proteins were differentially abundant between glioma and meningioma patients, including AMP4, CD276, LAMP1, NAPSA, LEG1, DNAS1, and BGAL." (PMID 32922940, 2020). "Interestingly, as a known positive regulator, CCL19 demonstrated relatively more negative correlations in glioma, with the most significant negative correlations with VEGFA, CD276, and HMGB1." (PMID 40714831, 2025).